DYNLT5 (dynein light chain Tctex-type family member 5)
Synonyms: TCTEX1D1; FLJ40873
Tractability: No criterion of Open Targets' tractability assessment is met for any kind of drug.
Gene: Protein-coding gene on chromosome 1 (66,751,741 to 66,779,051, forward strand). Ensembl gene ENSG00000152760.
Pathways (Reactome):
Organelle biogenesis and maintenance: Intraflagellar transport
Gene Ontology:
Molecular function: protein binding; dynein intermediate chain binding
Biological process: microtubule-based movement
Cellular component: cytoplasm; cytoplasmic dynein complex
Genetic constraint (gnomAD): Loss-of-function variants: 17 observed, 15.22 expected, observed/expected ratio (o/e) 1.12, 90% interval 0.76 to 1.66. The upper end of that interval is the gene's LOEUF score, 1.66, which puts it in group 6 of 6, group 1 being the genes least tolerant of losing a copy. Missense variants: 212 observed, 213.28 expected, observed/expected ratio (o/e) 0.99, 90% interval 0.89 to 1.11. Synonymous variants: 80 observed, 68.76 expected, observed/expected ratio (o/e) 1.16, 90% interval 0.97 to 1.4.
Homologues: Orthologues: chimpanzee DYNLT5 (97% identical), macaque DYNLT5 (92% identical), dog DYNLT5 (82% identical), pig DYNLT5 (80% identical), rabbit DYNLT5 (80% identical), guinea pig DYNLT5 (70% identical), mouse Dynlt5 (70% identical), tropical clawed frog dynlt5 (68% identical), rat Dynlt5 (66% identical), zebrafish dynlt5 (61% identical). Paralogues in human: DYNLT2B (25% identical), DYNLT2 (24% identical), DYNLT4 (24% identical), DYNLT3 (17% identical), DYNLT1 (15% identical).
Diseases named in the same sentence as DYNLT5 in open-access papers:
DYNLT5 is named in the same sentence as 6 diseases in open-access papers, as found by Europe PMC text mining. Sharing a sentence is not in itself a finding about the gene and the disease.
DYNLT5 shares sentences with these, for which no sentence is quoted: cancer (1 paper); cardiomyopathy (1); depression (1); Duchenne muscular dystrophy (1); endometrial cancer (1); lung carcinoma (1).